MSI2 (musashi RNA binding protein 2)
Diseases named in the same sentence as MSI2 in open-access papers (continued):
Sharing a sentence is not in itself a finding about the gene and the disease.
cancer (98 papers, 2007 to 2026). A tumor composed of atypical neoplastic, often pleomorphic cells that invade other tissues. "RNA-binding protein Musashi 2 (MSI2) is elevated in several cancers and is linked to poor prognosis." (PMID 37117191, 2023). "The loss of MSI2 reduced cancer stem cell frequency, increased differentiation, and impaired propagation of bcCML in mouse models in vitro and in vivo." (PMID 38234720, 2023). "MSI2 is an oncogene associated with differentiation, resulting in the preservation of cancer stem cells." (PMID 32848739, 2020). "The RNA-binding protein Musashi-2 (MSI2) has been implicated in the tumorigenesis and tumor progression of some human cancers." (PMID 32448269, 2020). "Higher expression of MSI2 is linked with aggressive cancer and poor prognosis of AML patients with normal karyotype." (PMID 31448224, 2019). "RNA-binding protein Musashi-2 (MSI2) is a key regulator in stem cells, it is over-expressed in a variety of cancers and its higher expression is associated with poor prognosis." (PMID 29290973, 2017). "Although these results suggest a correlation between increased Msi2 variant 2 expression and a subset of cancers, Msi2 variant 2 is expressed at quite low levels and so independent validation will be necessary to confirm these observations." (PMID 28912529, 2017). "Of 12 cancer types analyzed, Msi2 variant 2 transcript expression was upregulated in 9 cancer types across some, if not all stages of disease progression." (PMID 28912529, 2017). "Examining genome sequencing data from matched tumor-control pairs across nine diversecancer types, we found that Msi1 and Msi2 were notsignificantly mutated in most of these cancers." (PMID 25380226, 2014). "Additionally, cancer‐associated fibroblast‐derived MSI2 facilitates NSCLC metastasis by inducing epithelial–mesenchymal transition via paracrine IL‐6 signaling." (PMID 39969091, 2025). "The RBP Musashi-2 (MSI2), a member of the Musashi gene family, has been implicated in various physiological and pathobiological processes, such as controlling cell differentiation, tissue regeneration and cancer development." (PMID 38347600, 2024). "In KG-1α cells, overexpression of DLL1 could partially reverse the biological effect caused by knockdown of MSI2 through restoring the expression levels of the key factors of Notch1 signaling pathway and cancer stemness-related proteins." (PMID 37149661, 2023). "Notably, MSI2 has been implicated in cancer progression, particularly in the regulation of cell proliferation, metastasis, migration and invasion." (PMID 38041016, 2023). "Some cancer drivers displayed both decreased accessibility and decreased mRNA levels, e.g., Brca1, E2f7 and Myh11, while others displayed increased accessibility and associated mRNA upregulation, e.g., Msi2, Bace2." (PMID 35269430, 2022). "This may be because the MSI2 protein is encoded by the Msi2 gene, and its genetic mutations have been widely reported to be closely related to poor prognosis in cancers." (PMID 36713428, 2022). "Whether higher levels of MSI2 and hnRNPA2 found in cancer cells might favored their association with apigenin remains to be investigated." (PMID 33731677, 2021). "Upregulation of MSI2 variant 2 was observed in a large number of cancers by TCGA RNA-seq data sets." (PMID 31952541, 2020). "Moreover, interrogation of publicly available cancer RNA-seq data revealed significant upregulation of Msi2 variant 2 transcript expression in tumor vs normal control samples in 9/12 analyzed cancer types." (PMID 28912529, 2017). "Among these, CpG sites associated with ZNF667, TEAD1, HDAC4, MSI2, and CCM2 were predominantly hypermethylated, while malignant tumors overall exhibited lower methylation levels compared to the benign group." (PMID 41597272, 2026). "MSI2, an RNA-binding protein, has been widely studied in different cancer types, and its regulation is crucial for disease development." (PMID 39990676, 2025).
cancer (continued). "According to previous reports, MSI2 can interact with mRNAs and regulate the translation of several oncogenic proteins related to cancer signaling pathways, such as the TGFβ/SMAD, mTOR, PI3K/Akt, cMET, NUMB/Notch, cMyc, and Hh signaling pathways." (PMID 39990676, 2025). "Analyses of genes co-expressed with MSI2 further supported this assumption, suggesting involvement in multiple cancer hallmarks, mainly DNA maintenance and cell death resistance." (PMID 40843174, 2025). "Fang’s group further demonstrated the importance of MSI2 in cancer stem cell maintenance and chemoresistance." (PMID 38328550, 2024). "This mutation created novel splice junctions and altered the splicing patterns of multiple genes, including known drivers of cancer (e.g., MSI2)." (PMID 38730709, 2024). "MSI2 is upregulated in CRC and correlates with high levels of ferroptosis inhibitors, suggesting MSI2’s involvement in cancer cell survival and malignancy." (PMID 39456596, 2024). "Through MSI2 knockout models, 38 potential MSI2-targeted genes were identified, significantly enhancing the understanding of MSI2’s role in cancer biology." (PMID 39456596, 2024). "MSI2 regulates multiple critical biological processes in stem cells and cancer cells and contributes to cancer drug resistance." (PMID 37173995, 2023). "The histology of MSI2 knockdown tumors displayed more epithelial type cells while histology of MSI2 overexpression tumors displayed an increased nuclear/cytoplasm ratio, which was indicative of malignant tumor types." (PMID 37117191, 2023). "Increased expression of MSI2 is considered a prognostic indicator for poor clinical outcomes in different cancers including HCC." (PMID 37117191, 2023). "Musashi-2 (MSI2) is a critical RNA-binding protein (RBP) whose ectopic expression drives the pathogenesis of various cancers." (PMID 38041016, 2023). "Musashi-1 and MSI2 as RBPs have been found to be overexpressed in various cancer, as well as our current results that MSI2 was highly expressed in AML patients, leading to poor prognosis." (PMID 37149661, 2023). "Recently, MSI2 was reported to be a cancer driver gene and postulated to be a possible effector in the development of cancer." (PMID 36599932, 2023). "We observed that the key factors of Notch1 signaling pathway and cancer stemness-related proteins were downregulated when MSI2 is silenced and upregulated when it is overexpressed." (PMID 37149661, 2023). "MSI2 regulates several biological processes involved in cancer initiation, development and resistance to treatment, and deserves further investigation as a potential therapeutic target." (PMID 37107676, 2023). "To assess their impact, we conducted a targeted functional screen using primary cancer stem cells derived from Msi2-GFP reporter KPf/fC tumors 7, where cells were transduced with lentiviral shRNA or sgRNA, and growth was analyzed in sphere-forming conditions." (PMID 36653361, 2023). "The stem cell gene MSI2 is often hijacked and aberrantly upregulated in cancer, where it can drive sustained self-renewal of cancer stem cells, leading to tumor growth, therapy resistance, and disease progression." (PMID 38234720, 2023). "We demonstrate this approach by designing inhibitors of Musashi proteins MSI1 and MSI2, key regulators of mRNA stability and translation that are upregulated in many cancers." (PMID 36711552, 2023). "Conversely, MSI2 is a crucial regulator of cancer stem cell programs by acting on the stability and translation of target mRNAs that encode key proteins of oncogenic signaling pathways (e.g., TGFβR1/SMAD3, NUMB/Notch, PTEN/mTOR, MET, and MYC)." (PMID 37107676, 2023). "This is in accordance with the reported cell-type specific activities of the ubiquitous MSI2 in cell renewal, cell differentiation and cancer control in animals." (PMID 37773033, 2023).
cancer (continued). "MSI2 also maintains the self-renewal program in cancer by directly increasing the translation of MYC and other proteins, without significantly increasing their mRNA levels." (PMID 37117191, 2023). "MSI2, an oncogenic RNA-binding protein, is associated with the BCAT1 transcript and positively regulates its protein levels in those cancers." (PMID 37076565, 2023). "Smarcd3KO-KPf/fC tumors showed a trend towards reduced EpCAM+ tumor cell content, and a 2.5-fold reduction in EpCAM+MSI2+ cancer stem cells at midpoint (7–8 weeks)." (PMID 36653361, 2023). "Because CAFs interact with NSCLC cells to promote metastasis, and activated cell motility is a hallmark of cancer, we investigated the importance of CAF MSI2 in NSCLC cell migration and invasion." (PMID 37941042, 2023). "Previous studies have demonstrated that both PRMT5 and MSI2 maintain c-MYC expression in cancer cells through independent mechanisms, but we found MSI2 and PRMT5 cooperate by retaining c-MYC translation." (PMID 36167829, 2022). "Because we are interested in understanding the role of MSI2 in cancers where MSI2 is expressed, we established FLAG-tagged MSI2 expressed in K562 cells as a model system." (PMID 35528200, 2022). "Transcripts found translationally upregulated upon MSI2 knockdown were highly enriched within categories of cancer, cell cycle, cell death and differentiation." (PMID 35528200, 2022). "While our results show strong biochemical evidence of EIF3A regulation by MSI2, we acknowledge that the relevance of such a regulation in cancer can only be inferred, and hence a limitation of the study." (PMID 35528200, 2022). "Musashi 2 (MSI2) is an RNA-binding protein that regulates mRNA translation of numerous intracellular targets and plays an important role in the development of cancer." (PMID 36530989, 2022). "MSI2 is emerging as a regulator of multiple critical biological processes relevant to cancer initiation, progression, and drug resistance through maintaining CSC populations, including BCs." (PMID 35102250, 2022). "The RNA-binding protein Musashi-2 (MSI2) controls the translation of proteins that support stem cell identity and lineage determination and is associated with progression in some cancers." (PMID 34237057, 2021). "In the study, we aim to identify MSI2 RNA targets and small molecules inhibiting MSI2-dependent growth in cancer cells and developed novel strategies based on the knockout of MSI2." (PMID 35153752, 2021). "Several prior studies have identified roles for MSI2 as an oncogenic driver in multiple types of cancer." (PMID 34237057, 2021). "The identification of RNA targets in the cancer contexts allows to clarify the molecular function of MSI2 that is essential to define the MSI2-dependent carcinogenesis and the targeted therapeutic agents." (PMID 35153752, 2021). "Over the past decade, numerous studies have reported that the musashi(MSI) gene, in particular MSI2, is involved in the development of cancer in diverse forms." (PMID 33550985, 2021). "As a regulator of protein translation, MSI2 is positioned to influence expression of numerous cancer targets in addition to those identified here; based on the work presented here, further study in CRC is strongly merited." (PMID 34237057, 2021). "The specific biological functions of MSI2 and how it is involved in regulating the occurrence of cancer are described in detail in this paper." (PMID 33550985, 2021). "The RBP Musashi-2 (MSI2), a member of the Musashi gene family, has been characterized as a cancer-driver gene in some tumors." (PMID 32448269, 2020). "MSI1 and MSI2 share similar roles in stem cells and in cancer initiation and progression, but they also have distinct roles." (PMID 32784494, 2020). "MSI2 has important roles in maintaining stem cell populations and regulating cancer initiation, progression, and metastasis." (PMID 33553241, 2020).
cancer (continued). "The MUSASHI (MSI) family of RNA binding proteins (MSI1 and MSI2) contribute to a wide spectrum of cancers including acute myeloid leukemia." (PMID 31217428, 2019). "Several studies have indicated MSI2 as a translation regulator that contributes to a variety of cancers." (PMID 31053152, 2019). "Further studies on the relationship between Msi2 and signaling pathways in cancer and various malignancies, including CML is required." (PMID 31231484, 2019). "One such group of RBPs, Musashi proteins comprised of MSI1 and MSI2, has been long studied in neurogenesis and cancer biology." (PMID 30367664, 2018). "Based on these biological functions, MSI2 protein can regulate cancer invasion, metastasis and development of more aggressive cancer phenotypes, including drug and radiation resistance." (PMID 30419948, 2018). "For example, Msi-1 and Msi-2 are overexpressed in a number of human carcinomas (cancers of epithelial origin), but downregulated in others (rev." (PMID 29535610, 2018). "Our goal is to develop potent and specific MSI1/MSI2 inhibitors, and ultimately move these new inhibitors into clinical applications in the treatment of cancers with MSI overexpression." (PMID 30097032, 2018). "In cancer, MSI2 expression is elevated in hematologic malignancies, colorectal adenocarcinomas, lung, pancreatic cancers, and glioblastoma." (PMID 30097032, 2018). "As in cancer cells, overexpression of Msi2 inhealthy mammary gland tissue suppressed EMT and resulted in a defective mammary ductalbranching pattern." (PMID 25380226, 2014). "In NSCs, overexpression ofMsi1 or Msi2 impaired migration as assayed by ascratch assay as well (data not shown), consistent with the phenotype observed in LM2breast cancer cells." (PMID 25380226, 2014). "Musashi‐1 (MSI1) and Musashi‐2 (MSI2) are highly expressed in various cancers." (PMID 40761481, 2025). "Recent research has spotlighted the significance of Musashi2 (MSI2) in cancer biology." (PMID 38645664, 2024). "Overall, MSI2 overexpression increases cancer cell stemness and viability, highlighting its importance as a potential target for overcoming drug resistance and reducing cancer cell stemness in NSCLCs and other cancer types." (PMID 38328550, 2024). "Moreover, we extracted MSI2 gene expression data in standardized pan-cancer dataset and analyzed the difference between normal and tumor samples, as well as the relationship between gene expression and prognosis in each tumor." (PMID 37149661, 2023). "Although MSI2 has been associated with various aggressive cancer phenotypes, its impact on the TME has not been demonstrated." (PMID 37941042, 2023). "MSI2 (RNA‐binding protein Musashi homolog 2) is known to be an important regulator in cancer initiation, progression, and drug resistance, whereas DNMT3B (DNA Methyltransferase 3 Beta) mediates DNA methylation, and play a crucial role in in hematopoietic stem cells." (PMID 34862757, 2022). "Therapeutic efficacy of this MSI2 inhibitor on cancers of solid tumor including GBM remains unknown." (PMID 35158774, 2022). "In conclusion, elevated MSI2 expression is closely correlated with poor prognosis in various cancers, and may serve as a potential molecular target for cancer patients." (PMID 36530989, 2022). "MSI2, one of the two members of Musashi RNA-binding family, is participated in the post-transcriptional regulation via controlling the translation efficiency or target mRNA stability in many cancers." (PMID 35102250, 2022). "This discrepancy between bulk RNA–Seq and IHC data could result from a minor presence of MSI1+ cancer stem cells (CSCs) in these tumors or a potential cross–reactivity of the MSI1–directed antibodies with MSI2." (PMID 34062997, 2021).
cancer (continued). "Cancer cells often alter or lose multiple pathways and thus might become uniquely dependent on MSI2 regulation." (PMID 32332729, 2020). "Interestingly, it has previously been shown that MSI2 can contribute to chemotherapeutic resistance in different cancer models." (PMID 31217428, 2019). "MSI2, an RNA-binding protein, is a central regulator of the translation of cancer stem cell programmes and may be a target gene of HMGA2." (PMID 31053152, 2019). "In addition, we demonstrate that two SOX2-associated proteins, MSI2 and Ubiquitin Specific Peptidase 9x (USP9X), which have been recently implicated in the growth of other cancers, are required to support the growth and survival of DAOY cells and two GB tumor cell lines, U87 and U118." (PMID 23667531, 2013). "Thus, our work demonstrating that MSI2 translocations can be oncogenic in the context of bcCML may open new avenues and provide a paradigm for understanding how dysregulation of this pathway may be oncogenic in a wider array of cancers." (PMID 41498402, 2026). "A paradigmatic example is Musashi-2 (MSI2), an oncogenic RBP that governs multiple hallmarks of cancer through modulation of pivotal signaling pathways." (PMID 41049614, 2025). "Musashi-2 (MSI2), an RNA-binding protein, is known to be overexpressed and plays a critical role in enhancing cancer stemness and drug resistance in NSCLCs." (PMID 38328550, 2024). "These mutations represent additional insight into how genes such as IGF1R, MSI2, MBD2, and ASCL1 can be aberrantly regulated in cancer, highlighting the importance of expanding the field’s view of cancer genomics to include alterations in UTRs." (PMID 37516102, 2023). "Thus, our work demonstrating that MSI2 translocations can be oncogenic in context of bcCML may provide a paradigm for understanding how dysregulation of this pathway may be oncogenic in a wider array of cancers." (PMID 38234720, 2023). "Collectively, these findings indicate that the MSI2/HOXA9 fusion protein has oncogenic activity and can cooperate with BCR-ABL to drive cancer progression." (PMID 38234720, 2023). "Musashi 2 (MSI2) is an RNA binding protein (RBP) that regulates asymmetric cell division and cell fate decisions in normal and cancer stem cells." (PMID 35528200, 2022). "In contrast to MSI2, for which oncogenic potential and expression was predominantly reported in leukemia, MSI1 expression was shown in a variety of human cancers, primarily solid cancers." (PMID 34062997, 2021). "Musashi-2 (MSI2) shares a high degree of sequence identity to MSI1, functions redundantly in certain tissues, and is also overexpressed in many cancers." (PMID 32784494, 2020). "MSI‐2 protein was elevated in CRC tissues and mainly localized in the cytoplasm of the cancer cells." (PMID 26775684, 2016). "In an analysis of 24 breast tumours, rearrangements were found in known cancer genes including BRAF, PAX3, PAX5, NSD1, PBX1, MSI2 and ETV6, each of which is a partner in a fusion gene in several other human cancers." (PMID 24792170, 2014). "Additionally, MSI2 upregulation positively regulated NANOG expression, thereby enhancing cancer stem cell characteristics." (PMID 38328550, 2024). "To investigate this possibility, we intersected the genes whose AS was affected by apigenin with experimentally validated substrates of hnRNPA2, MSI2, or CELF1 identified by CLIP-seq (Crosslinking and Immunoprecipitation followed by deep sequencing) in cancer cells." (PMID 38092740, 2023). "HCC patient specimens were stained for MSI2, MYC and NANOG to test if MSI2-mediated MYC translation is TIC-specific or if non-TIC bulk cancers also show a similar tendency." (PMID 37117191, 2023). "It would be interesting to investigate whether the mechanism of resistance to PRMT5-targeted therapies mediated by the oncogenic axis, MSI2/c-MYC/BCL-2, could be extrapolated to the other cancers." (PMID 36167829, 2022).